ACLY (ATP citrate lyase)
Diseases named in the same sentence as ACLY in open-access papers (continued):
Sharing a sentence is not in itself a finding about the gene and the disease.
tumor (continued). "Decreased Acetyl-CoA–producing enzymes (ACLY) expression reduces tumor cell viability and inhibits tumor progression in glioblastoma, melanoma cancer, PDAC and prostate cancer." (PMID 38685045, 2024). "We found that polyunsaturated fatty acids significantly inhibited the proliferation of ACLY-knockdown tumor cells." (PMID 39399493, 2024). "The development of tumor cells and immune cells is affected by the expression of ACLY and its product AcCoA." (PMID 37064872, 2023). "The pathway of AcCoA synthesis by acetyl-CoA synthetase (ACSS) can bypass the inhibition of ACLY, which makes tumor cells resistant to ACLY inhibitors." (PMID 37064872, 2023). "The expression of ACLY in tumors is greater than that in normal tissue and is closely related to tumor stage and prognosis." (PMID 36994237, 2023). "The enhancement of the de novo fatty acid synthesis pathway is the main manifestation of lipid metabolism reprogramming in tumor cells, which involves a variety of key enzymes, mainly including increased expression of ACLY, ACC, and FASN." (PMID 36994237, 2023). "SREBP is a transcription factor that promotes DNL by upregulating key enzymes such as ACLY, FASN, and SCD, which are closely linked to tumor proliferation, apoptosis, and invasion." (PMID 37700339, 2023). "Our findings indicated that the upregulation of ACLY is involved in protecting tumor cells from ER stress." (PMID 37122003, 2023). "We used a vector that can carry the ShRNA-ACLY gene (by intravenous injection) to knockout the ACLY gene from tumor cells to kill the tumor or restore the sensitivity of the tumor to sorafenib in vivo." (PMID 35154461, 2022). "ACLY upregulation enhances tumor cell development, whereas ACLY silencing decreases tumor cell growth." (PMID 36358687, 2022). "Our analysis of TCGA dataset shows that only ACLY mRNA expression is significantly increased in tumor tissues compared with normal/benign tissues, whereas ACSS2 mRNA is expressed at the reduced levels in tumors samples." (PMID 36497382, 2022). "The genes up-regulated in the tumor tissues included ATP citrate lyase (ACLY) and monoamine oxidase A (MAOA)." (PMID 36090054, 2022). "In this study, we found that ACLY robustly promote lipid metabolism in GC cells, which further facilitate tumor cell migration and transwell." (PMID 36064336, 2022). "We found high expression of ACLY in all the tumor cells compared with that in normal fibroblast WI‐38 cells and breast MCF10A cells." (PMID 34747157, 2022). "This study suggests that activation of ACLY in T cells can inhibit tumor growth by promoting the proliferation of T cells." (PMID 34050894, 2022). "We measured changes in the expression of ACLY protein in the tumor tissues of the four groups by IHC." (PMID 35154461, 2022). "In vivo experiments demonstrated overexpression of ACLY promoted tumor growth and significantly increased tumor weight and volume." (PMID 36241648, 2022). "The acetylation of ACLY increases the ACLY stability by blocking its ubiquitinylation and degradation, which leads to the promotion of de novo lipid synthesis and tumor growth." (PMID 36613455, 2022). "Acetylation of ACLY stabilizes it by preventing ubiquitylation and degradation, and it stimulates de novo lipid synthesis and tumor cell proliferation, whereas deacetylation of ACLY by a deacetylase, such as SIRT2, destabilizes it." (PMID 36358687, 2022). "In particular, the ubiquitin-dependent degradation of ACLY is inhibited by the downregulation of a protein called Cullin3 (a tumor suppressor); this protein is essential for forming the ubiquitin ligase complex needed for this process." (PMID 35159223, 2022). "ACLY is expressed at the highest levels in the liver and white adipose tissue, and ACLY is upregulated and activated in a variety of tumor tissues." (PMID 35392171, 2022). "Acetylated ACLY promotes de novo lipid synthesis, cell proliferation, and tumor progression in lung cancer." (PMID 34050894, 2022).
tumor (continued). "In this way, we inhibited ACLY expression in transplanted tumors to inhibit the growth of tumor cells and restore the drug sensitivity of drug-resistant cells." (PMID 35154461, 2022). "ACLY is generally overexpressed in tumor cells, and its knockdown inhibits lipid synthesis in lung and prostate cancer cells, as well as tumor growth." (PMID 34047477, 2021). "Statistical significance was computed under Wilcoxon test, and ACLY expression was significantly higher (p < 0.001) in various types of tumor including HCC." (PMID 34344378, 2021). "In fact, mRNA levels of enzymes of FA synthesis pathway was significantly increased in tumor cells, including ACLY, ACACA, and FASN." (PMID 34206240, 2021). "ACLY can be regulated by growth factor stimulation, which is also required for histone acetylation and gene expression, and inhibition of ACLY results in tumor growth arrest." (PMID 33916219, 2021). "It is well documented that ACLY overexpression can maintain the malignant proliferation of various tumour cells and promote their malignant evolution." (PMID 33393219, 2021). "Previous studies have showed that ACLY inhibitor (SB‐204990) or ACLY knockdown restrains tumour cell proliferation and survival in a variety of tumours." (PMID 33393219, 2021). "Glucose and lipid metabolism are closely related in tumor cells, and ACLY links aberrant glucose and lipid metabolism." (PMID 34047477, 2021). "Several research groups demonstrated that ACLY knockdown or inhibition arrests the growth of tumor cells both in vitro and in vivo." (PMID 33679780, 2021). "MiRNA 22 inhibited the proliferation and invasion of tumor cells, and promoted apoptosis by down-regulating ACLY." (PMID 33833775, 2021). "Consistently, several researches have suggested ACLY is significantly up‐regulated in a variety of tumours, promoting tumour progression and metastasis." (PMID 33393219, 2021). "Immunohistochemistry also showed increased ACLY expression in tumor tissue compared with normal tissue." (PMID 34344378, 2021). "In this study, we have identified a novel function of SIRT6 in controlling nuclear levels of ACLY and ACLY-dependent tumor suppressive gene regulation." (PMID 34573442, 2021). "In our study, clinicopathological parameter sage, tumor stage, lymphatic, hematogenous metastases and SUCLG2, SUCLG1, ACLY, SUCLG2P2, ATIC and ACO2 genes were found to be associated with survival in univariable or multivariate analysis." (PMID 34589110, 2021). "In this context, PGC1α promotes tumor growth and loss of PGC1α leads to a reduction in CIC and ACLY expression and to blunting of tumor growth, an effect recapitulated by inhibition of fatty acid synthesis." (PMID 33499062, 2021). "The overexpression of ACLY and IGF1R was correlated with a higher risk of lymph node and distant metastasis, worse tumor differentiation, and higher AJCC stage." (PMID 34075028, 2021). "ACLY promotes tumor growth in glycolytic tumors, and its inhibition is responsible for the halt in tumor growth and leads to the differentiation of tumor cells." (PMID 34603386, 2021). "Oncogenic KRAS signaling in murine pancreatic acinar cells also promotes elevated histone acetylation in an AKT- and ACLY-dependent manner, even prior to tumor formation, and genetic deletion of Acly suppresses pancreatic carcinogenesis." (PMID 34109280, 2021). "Accordingly, a study reported that genetic or chemical inhibition of ACLY reduces, both in vitro and in vivo, proliferation, and tumor growth." (PMID 33808259, 2021). "FASN is found upregulated in prostate and breast cancer, and ACLY has been shown to support tumor formation and transformation." (PMID 33194695, 2020). "For example, the expression of ACLY is higher in various types of tumour tissues than that in adjacent normal tissues." (PMID 33118286, 2020). "CUL3-KLHL25 E3 ligase can inhibit lipid synthesis and tumor growth by targeting ATP citrate lyase (ACLY) for ubiquitination and proteolysis." (PMID 33004065, 2020).
tumor (continued). "ACLY inhibition by a pharmacological inhibitor or RNAi reduced both tumor growth in mouse xenografts and proliferation of tumor cells in vitro, inducing cell differentiation." (PMID 32679735, 2020). "ACLY is an enzyme that interconnects glucose and glutamine metabolism and it is essential for tumor metabolism as well as tumor proliferation." (PMID 31554283, 2019). "Similar to UBR4-mediated ubiquitylation, Cullin 3 containing E3 ligase complex has also been reported to ubiquitylate ACLY at Lys546 which inhibits lipid synthesis and tumor progression." (PMID 31534141, 2019). "ATP‐citrate lyases (ACL) play critical roles in tumour cell propagation, foetal development and growth, and histone acetylation in human and animals." (PMID 30582769, 2019). "Stable knockdown of ACLY induced differentiation of A549 lung adenocarcinoma and K562 chronic myelogenous leukemia cells, and suppressed tumor growth, in vivo." (PMID 29342092, 2018). "The ACLY inhibitor SB-204990 strongly inhibits tumor growth in mice with lung, prostate or ovarian cancer xenografts." (PMID 29784041, 2018). "Akt enhances the phosphorylation and activation of ACLY, and ACLY inhibition results in tumor growth arrest." (PMID 30347859, 2018). "Synthesizing acetyl-CoA and oxaloacetate from citrate and CoA, ACLY is the key regulator between aerobic glycolysis and amino acid as well as de novo lipid synthesis involved in proliferation of tumour cells." (PMID 30275468, 2018). "Second, the α2M*/CS-GRP78 axis induced ACLY and ACSS1 expression is then associated with acetyl-CoA production which activates acetylation of histone and proteins for tumor growth." (PMID 29296215, 2017). "We recently showed that the α2M*/CS-GRP78 axis regulates ACLY-dependent lipogenesis through the AKT pathway for the proliferation of glycolytically converted tumor cells." (PMID 29296215, 2017). "It has recently been reported that ACLY is required for cyclin E-mediated transformation, migration and invasion of breast cancer cells in vitro, as well as for tumor growth in vivo." (PMID 28412757, 2017). "Markedly elevated ACLY levels were uniformly observed across the four types of tumor tissues, yet the positive staining was hardly found in normal adjacent tissue (NAT) specimens." (PMID 27317765, 2016). "The upregulated of ACLY has been reported as one of the common features during this metabolic remodeling, which contributes to tumor formation, proliferation and survival." (PMID 27317765, 2016). "In this study, we have identified a novel link between miR-22, lipid anabolism and tumor suppression via downregulating the key metabolic enzyme ACLY." (PMID 27317765, 2016). "ACLY expression in tumor tissue was detected in both, cytoplasm and nucleus, whereas ME was detectable only in the cytoplasm." (PMID 25962060, 2015). "ATP citrate lyase (ACL) converts cytosolic citrate into acetyl-CoA, and is a rate-limiting step for FA synthesis in tumor cells." (PMID 26625127, 2015). "In vitro and in vivo studies indicate that new pharmacological agents inhibiting ACLY can lead to significant decrease in cellular and tumor growth." (PMID 25962060, 2015). "Gene expression patterns from human tumor samples were then separated by their similarity to our developed gene signatures associated with loss of ETV4 (shETV4), ACC1 (shACC1) and ACLY (shACLY)." (PMID 26452058, 2015). "SB-204990, an inhibitor of ACLY that has been shown to lower hepatic cholesterol and FA synthesis rates in rats, also reduced tumor formation in lung and prostate xenografts." (PMID 26452259, 2015). "The analysis of 10 patients with tumors located in the oral cavity revealed increase in cell cycle regulatory SKP2 (p = 0.0214) and metabolic ACLY gene (p = 0.0403) in the tumor tissues compared to the healthy tissues." (PMID 25575813, 2015). "In agreement with our in vitro findings, tumours with wild type CIC (n=5) showed elevated levels of either ACLY or pACLY compared to tumours with mutant CIC proteins (n=5)." (PMID 25277207, 2014).
tumor (continued). "Strikingly, a tumour sample with a truncated CIC protein (P79X) showed dramatic reductions in ACLY and pACLY." (PMID 25277207, 2014). "Reduction in ACLY/pACLY levels in our cells and in 1p19q co-deleted tumours expressing mutant CIC is consistent with the notion that mutations in CIC facilitate the diversion of citrate towards the production of 2HG." (PMID 25277207, 2014). "ATP citrate lyase follows, supporting aberrant transaminations with glutaminolysis and tumor lipogenesis." (PMID 21649891, 2011). "In highly proliferating cells, the enzyme ATP citrate lyase (ACL) uses citrate as a carbon source to generate fatty acids, and disruption of ACL impairs tumor growth." (PMID 24281221, 2010). "ATP citrate lyase (ACLY) catalyses the conversion of citrate to cytosolic acetyl-CoA, thus linking the tumour-associated increase in glycolysis to enhanced lipogenesis." (PMID 19352381, 2009). "Tumor cells increasingly rely on de novo fatty acid synthesis, supported by key enzymes such as ATP citrate lyase (ACLY), acetyl‐CoA carboxylase (ACC1), fatty acid synthase (FASN), and stearoyl‐CoA desaturase 1 (SCD1), which together promote membrane biogenesis, signaling, and energy supply." (PMID 41163383, 2025). "ACLY expression and activity are increased in a variety of tumor types and, considering its role in generating acetyl-CoA, ACLY inhibition could represent a well-tolerated therapeutic strategy." (PMID 40814339, 2025). "Thus, combination therapy with ACSS2 inhibitors can effectively inhibit acetate‐dependent tumor development and increase the antitumor efficacy of ACLY inhibitors." (PMID 41346571, 2025). "Notably, the ACSS family (notably ACSS2) can synthesize acetyl‐CoA via acetate metabolic bypass, which induces drug resistance in tumor cells to ACLY inhibitors." (PMID 41346571, 2025). "ATP citrate lyase (ACLY) converts citrate into acetyl-CoA, linking glucose and lipid metabolism, and inhibiting ACLY reduces lipid synthesis, cell proliferation, and tumor growth in GBM." (PMID 39859381, 2025). "Given that ccRCC is characterized as a “metabolism-related disease,” particularly in terms of lipid metabolism, the unexplored HIF-2α/LPCAT1/ACLY pathway may present a promising therapeutic target for controlling this tumor." (PMID 39781455, 2025). "Given the immunosuppressive nature of the MASH-HCC microenvironment and the emerging links with metabolism, we hypothesized that ACLY may serve as a key metabolic regulator of tumour–immune interactions." (PMID 40739358, 2025). "To further validate the role of ACLY, we established a nude mouse xenograft tumor model." (PMID 41051446, 2025). "In addition, we performed Oil Red O staining and IHC staining for ACLY in tumor tissue from the subcutaneous xenograft model and revealed significantly reduced lipid droplet content and ACLY expression in the xenograft tissues of the RNF112 group." (PMID 40178292, 2025). "Lower expression levels of FASN and ACLY may reduce citrate catabolism and generate a massive deregulation of de novo lipogenesis pathway, increasing gemcitabine uptake and improving tumor response." (PMID 38425123, 2024). "Since ACLY has been shown to support tumor growth, we used data from The Cancer Genome Atlas (TCGA) to form hypotheses about the function of ACLY splice isoforms." (PMID 38815867, 2024). "Furthermore, ACLY inhibitor dramatically suppressed tumour growth and lipid metabolism in ESCC cells xenografted tumour model, whereas ACLY overexpression displayed the opposite effect." (PMID 38426936, 2024). "Additionally, ACLY can facilitate tumor stemness through the downstream effectors, such as overexpression of ACLY enhances the expression of Snail, an EMT master regulator, thereby promoting EMT and stemness." (PMID 38994204, 2024). "Furthermore, nuclear acetyl-CoA production by ACLY facilitates homologous recombination and induces tumor cell resistance to DNA-damaging drugs." (PMID 39399493, 2024).
tumor (continued). "Therefore, we propose that inhibiting ACLY promotes ferroptosis by increasing the tumor cells’ uptake of PUFAs, which are then subject to lipid peroxidation under oxidative stress." (PMID 39399493, 2024). "We acknowledge that the Akt/ACLY signaling axis may play several other roles in TNBC tumor progression, for example, in DNA repair; however, here, we chose to focus on histone acetylation as a potentially relevant downstream effect." (PMID 38731867, 2024). "It was reported that ACLY was acetylated at K540, K546, and K554 by p300/CBP-associated factor (PCAF), which blocked poly-ubiquitination at these sites and stabilized ACLY under high-glucose conditions, lipid synthesis, and tumor growth." (PMID 39085201, 2024). "However, ACLY knockdown in HPS cells abolished the stellate cell-mediated increase in tumour burden and proliferative tumour cell population from co-implanted S2-013 cells." (PMID 38429478, 2024). "Inhibition of ACLY activity can significantly inhibit the proliferation of tumor cells." (PMID 36994237, 2023). "Moreover, ACLY-mediated regulation of acetyl-CoA production is also crucial for tumor metabolic reprogramming." (PMID 37122003, 2023). "Studies have shown that inhibition or knockdown of ACLY can increase the production of ROS, thereby inhibiting the proliferation of tumor cells and inducing apoptosis, but the mechanism of ROS content enhancement remains unclear." (PMID 36994237, 2023). "ACLY promotes tumor invasion and metastasis by regulating the Wnt/β-catenin signaling pathway." (PMID 37064872, 2023). "Additionally, the ACLY inhibitor bempedoic acid showed potent anti-tumor activity against all stable cell lines 24 h after the combined treatment, and a significantly lower rate of decrease in IC50 was observed in Lv-MCF7." (PMID 37958642, 2023). "In addition, PD-1 regulates ACLY, which uses extramitochondrial citrate to fuel acetyl-CoA pools for histone acetylation and enables aberrant AP-1 activity in the tumor cells." (PMID 37723306, 2023). "ACLY has been demonstrated to be aberrantly expressed in a variety of tumor types." (PMID 36983670, 2023). "At the clinical level, ACLY expression in HCC was related to the degree of tumor differentiation." (PMID 35154461, 2022). "Furthermore, the acetylation level of H3K27 on caveolin‐1 promoter was increased by FABP7wt overexpression, suggesting FABP7 regulates caveolae formation through the interaction with ACLY, leading to activated tumor proliferation." (PMID 34716958, 2022). "Our findings also highlighted the notion that ACLY may be a promising therapeutic target in GC and provides evidences for uncovering the link between lipodystrophy and tumor development." (PMID 36064336, 2022). "Moreover, blockages of ATM, MAPK, and mTOR signaling with respective inhibitors prevented citrate‐induced upregulation of ACLY in tumor cells." (PMID 34747157, 2022). "The overexpression of ACLY has been observed in multiple tumor types before." (PMID 35681609, 2022). "Therefore, compared with normoxia, hypoxia not only induced tumor cells to become more resistant to sorafenib but, in the case of high glucose metabolism, the recovery of drug sensitivity of tumor cells was also more significant after ACLY-knockout." (PMID 35154461, 2022). "More interestingly, compared with normoxia, inhibiting ACLY under hypoxic conditions could significantly inhibit fatty-acid synthesis in tumor cells and the Warburg effect, and the resistance of tumor cells to sorafenib was also reversed significantly." (PMID 35154461, 2022). "Prior studies have shown that ACLY is promotes lipid synthesis and enhancing β-catenin signaling, while the elevation of lipid synthesis and β-catenin signaling activity can accelerate tumor progression." (PMID 36309693, 2022). "ACLY is involved in lipid biogenesis and plays a vital role in tumor progression." (PMID 36241648, 2022).